CXCR4 (C-X-C motif chemokine receptor 4)
Diseases named in the same sentence as CXCR4 in open-access papers (continued):
Sharing a sentence is not in itself a finding about the gene and the disease.
breast carcinoma (continued). "These evidences provide insight into the molecular mechanism that explains why GLI1 expression and CXCR4/CXCR7 axis are both linked to a poor prognosis of breast cancer patients." (PMID 26413813, 2015). "Involvement of CSCs in tamoxifen resistance of breast cancer cells has been reported, which appears to be mechanistically linked with higher expression of CXCR4, STAT3, Sox2, EZH2, and lower expression of CD24." (PMID 26206152, 2015). "The present study aimed to investigate the influence of CXCR4 rs2228014 polymorphism on its mRNA and protein expression in breast cancer samples." (PMID 26576337, 2015). "Many retrospective studies have documented that the expression of various chemokine receptors, particularly CXCR4, was associated with a poor prognosis in patients with melanoma and breast cancer." (PMID 26576337, 2015). "A meta-analysis investigation based on thirteen eligible studies, consisting of 3,865 patients with breast cancer, demonstrated that the overexpression of CXCR4 was significantly associated with lymph node status and distant metastasis." (PMID 25901761, 2015). "CXCR4 over-expressing in human breast cancer tissues was linked to the nodal spread of breast cancer." (PMID 25753200, 2015). "We found that breast cancers with CXCR4 expression were associated with lymph node status (pooled RR =1.20, 95% CI: 1.01-1.43, P<0.001) and distant metastasis (pooled RR =1.52, 95% CI: 1.17-1.98, P = 0.125)." (PMID 24475985, 2014). "CXCR4 is another adhesion molecule that has been implicated in the acquisition of invasive and metastatic phenotypes in several cancer types, such as breast cancer, melanoma, prostate cancer and renal cancer." (PMID 24587095, 2014). "High CXCR4 tumour expression is associated with poor prognosis of lung, brain, CNS, blood and breast cancers." (PMID 24205302, 2013). "CTCE-9908 is a synthetic peptidic antagonist that reduces the formation of experimental lung and bone metastasis caused by CXCR-4 expressing breast cancer cells." (PMID 26237142, 2013). "CXCR4 expression has been established as a prognostic marker in many cancer cell types including breast carcinomas, and the SDF-1α-CXCR4 signaling axis has been associated with breast cancer metastasis." (PMID 23484027, 2013). "The attraction of SDF-1α and CXCR4 causes breast cancer cells to migrate into these organs, where they proliferate and form metastastes." (PMID 23082154, 2012). "Overexpression of c-erbB-2 and CXCR4 in breast cancer was considered a risk factor and was associated with the shortest survival times." (PMID 23046610, 2012). "CXCL12 and its receptor CXCR4 are implicated in the metastasis of several cancers including breast cancer metastasis to lung and lymph node." (PMID 23024796, 2012). "The SDF-1α receptor CXCR4 has been linked to the organ-specific metastatic spreading of breast cancer." (PMID 22487193, 2012). "The attraction effect between CXCL12 and CXCR4 causes breast cancer cells and non-small cell lung cancer cells to migrate into brain, where cancer cells proliferate and form metastatic tumors." (PMID 23443093, 2012). "Research has shown CXCR4 to be implicated in the invasion and metastasis of several cancers, including carcinoma of the breast." (PMID 22295222, 2011). "For breast cancer, Hessol and colleagues postulated that CXCR4-expresing HIV virions reduce breast cancer risk by inducing apoptosis of neoplastic breast cells via interaction with the CXCR4 receptor, which is expressed on some breast cancer cells." (PMID 22004990, 2011). "Chemokine SDF1α and its unique receptor CXCR4 have been implicated in organ-specific metastases of many cancers including breast cancer." (PMID 20492653, 2010). "Breast cancer risk was significantly and independently reduced with CXCR4 tropism (adjusted odds ratio, 0.10, 95% CI 0.002–0.84) and with menopause (adjusted odds ratio, 0.08, 95% CI 0.001–0.83)." (PMID 21179547, 2010).
breast carcinoma (continued). "Su examined 85 cases of early breast carcinoma and learned that high cytoplasmic expression of CXCR4 is associated with axillary nodal metastasis." (PMID 20181250, 2010). "The molecular mechanisms underlying the action of CXCR4 on breast cancer cell invasion are currently under intense investigation." (PMID 21167057, 2010). "We found a 90% lower risk of breast cancer for women who have circulating CXCR4-tropic HIV envelope, which points to the possibility of a novel protective interaction between a specific viral protein and cancer risk." (PMID 21179547, 2010). "We further demonstrated that upregulation of CXCR4 in breast cancer cells secondary to hypoxia is associated with increased chemotactic ability and metastatic potential, and that this effect can be abrogated by CXCR4 attenuation." (PMID 20492653, 2010). "Secretion of stromal cell-derived factor-1 (SDF-1)/CXCL12 and expression of CXCR4 have been identified to be associated with breast cancer metastasis." (PMID 20652010, 2010). "Activation of CXCR4/CXCL-12 signaling plays a critical role in growth and invasion of primary and metastatic breast tumors; CXCR-4 expression is a hallmark of a subset of stem breast cancer cells, with metastatic behavior and homing to bone." (PMID 19226458, 2009). "YY1 has also been implicated in the negative regulation of the chemokine receptor CXCR4, which has been implicated in the ability of breast cancer cells to metastasize to bone." (PMID 19566924, 2009). "The chemokine receptor Cxcr4 is another protein that has been associated with an unfavorable outcome and the occurrence of lymph node metastasis in breast cancer." (PMID 19583841, 2009). "The findings that cytoplasmic CXCR4 expression is elevated in breast cancer samples, and that higher expression of CXCR4 is associated with parameters of tumour aggressiveness, and a poor prognosis was later confirmed in an independent patient population." (PMID 17245339, 2007). "This induces the activation of integrins on CXCR4-expressing breast cancer cells which causes transendothelial migration of the cells followed by growth and angiogenesis resulting in secondary tumours." (PMID 17726466, 2007). "Over expression of the inhibitor of NF-κB (IκB) in breast cancer cells constitutively expressing NF-κB results in reduced expression of CXCR4 and a corresponding loss of SDF-1α-mediated migration in vitro." (PMID 15978137, 2005). "Recently, studies implicated CXCR4 in chemotaxis, invasiveness and metastasis of tumours, particularly in metastasis of breast cancer, in an organ-specific manner." (PMID 15987445, 2005). "Additionally, the (CK+CXCR4+JUNB+) phenotype in bone marrow disseminated tumor cells (DTCs) of early breast cancer patients is strongly linked to poorer OS." (PMID 39575761, 2025). "Overexpression of the inhibitor of nuclear factor kappa-B kinase (IKK) in breast cancer cells with constitutive NF-κB activity resulted in reduced expression of the receptor CXCR4 in vitro and the corresponding loss of migration mediated by its ligand, the SDF-1α." (PMID 36701089, 2023). "For instance, when human breast cancer cells with constitutive NF-κB activity were treated with NF-κB inhibitors, (overexpression of IκBα or parthenolide treatment), the expression of CXCR4 transcripts was notably reduced, followed by a loss of SDF-1α-mediated migration." (PMID 37853467, 2023). "Here, we hypothesize that the CXCL12/CXCR4/mTOR/HIF-1α axis in DPP-4-deficient cells plays a key role in the activation of autophagy in breast cancer cells to promote survival." (PMID 37760498, 2023). "Importantly, high expression of CXCR4 in breast cancer has been associated with a higher incidence of distant metastasis and bone metastasis as compared to low CXCR4 expression." (PMID 34831167, 2021). "The expression levels of the cytokine receptor CXCR4 are associated with invasiveness and aggressiveness in more than 20 human neoplasias, including colorectal cancer and breast cancer." (PMID 34834337, 2021).
breast carcinoma (continued). "The mir-222/CXCR4 pathway is not only implicated in GDM but also in breast cancer." (PMID 34199293, 2021). "Similarly, several previous studies have shown an association between high CXCR4 expression and breast cancer metastasis." (PMID 34535679, 2021). "We detected a significant increase in the specific FRET signal over the control in invasive breast cancer cell lines only, suggesting that the CXCR4 and CCR7 association may be linked to the invasive breast cancer phenotype." (PMID 34685420, 2021). "On the contrary, high cytoplasmic CXCR4 localization was reported to be favorable for triple-negative breast cancer and adenocarcinoma of the lung but has been independently associated with lymph node metastasis of breast cancer in another analysis." (PMID 33281749, 2020). "Interestingly, HER2 receptor tyrosine kinase can also cause an upregulation of CXCR4 expression that can mediate breast cancer invasion." (PMID 32630806, 2020). "In addition, it has been found that fibroblast‐derived CXCR4 promotes breast cancer growth and is associated with poor prognosis." (PMID 32253815, 2020). "CXCR4, a cell surface chemokine receptor, is implicated in the growth, invasion, angiogenesis and metastasis in a wide range of malignant tumors, including leukaemia, breast cancer and very recently in glioma." (PMID 31382985, 2019). "The protein CXCL12 and its receptor CXCR4 has been associated with breast cancer migration." (PMID 30416486, 2018). "Indeed, bone-seeking breast cancer cells express high levels of CXCR4, which is associated to cancer-cell stemness." (PMID 29461491, 2018). "However, the breast cancer apoptosis had variable correlation to the CXCR4 functional responses pointing to a possible CXCR4-linked secondary mechanism that our assays were not capable of measuring." (PMID 29682200, 2018). "CXCR4 is required for leukocyte trafficking and is implicated in breast cancer metastasis." (PMID 29973594, 2018). "Several in vitro studies have previously demonstrated that CXCR4 is overexpressed in breast cancer and might be therefore an interesting target for diagnostic and therapeutic approaches." (PMID 30191351, 2018). "Additionally, the reduced CXCR4 by chitosan nanoparticle-delivered siRNA was associated with increased sensitivity of breast cancer cells to cisplatin." (PMID 28446538, 2017). "In this study, CXCR4 is strongly associated with pregnancy, which could have implications for our understanding of pregnancy-associated breast cancer risk." (PMID 27888192, 2017). "Moreover, the reduced CXCR4 expression was associated with increased sensitivity of breast cancer cells to cisplatin." (PMID 28446538, 2017). "Moreover, the reduced CXCR4 by chitosan nanoparticle-delivered siRNA was associated with increased sensitivity of breast cancer cells to cisplatin." (PMID 28446538, 2017). "In our previous study, we established that HRG-induced activation of P-Rex1/Rac1 and motility in luminal breast cancer cells is mediated by transactivation of CXCR4, a G-protein-coupled receptor widely associated with breast cancer cell metastatic dissemination." (PMID 27351228, 2016). "Importantly, recent meta-analysis validated CXCR4 as a prognostic marker for breast cancer and demonstrated the association of high CXCR4 expression with lymph node status, distant metastasis, and poor overall and disease free survival." (PMID 25909161, 2015). "A recent nested case–control study from the Women’s Interagency HIV Study and HIV Epidemiology Research Study cohorts showed that a low risk of breast cancer may be linked to infection with CXCR-4 tropic virus." (PMID 25885746, 2015). "In addition, we investigated the effects of CXCR4 gene polymorphism on the breast cancer clinicopathological development." (PMID 26576337, 2015).
breast carcinoma (continued). "Our study focused on these parallel characteristics in several culture models, based on the transfection of CXCR4, a widely accepted chemokine receptor implicated in metastasis of breast cancer cells that also is overexpressed in breast cancer stem cells (CSC)." (PMID 26528758, 2015). "Furthermore, expression of CXCR4 increases the risk of metastasis to the liver in patients with axillary node-positive primary breast cancer." (PMID 25885919, 2015). "However, breast cancers with CXCR4 expression were associated with lymph node status (pooled RR =1.20, 95% CI: 1.01-1.43, P<0.001 and I2 = 80.9 random-effect) and distant metastasis (pooled RR =1.52, 95% CI: 1.17-1.98, P = 0.125 and I2 = 42.1 random-effect)." (PMID 24475985, 2014). "Moreover, in breast cancer, CXCR4 interacts with the EGFR variant, EGFR vIII, a constitutively active mutant highly expressed in cancer stem cells, to regulate invasion via p38 MAPK." (PMID 25484899, 2014). "Disruption of the CXCR4 signaling pathway using neutralizing antibodies or synthetic peptide antagonists have been shown to reduce the formation of lung and bone metastases caused by CXCR4-expressing breast cancer cells in preclinical models." (PMID 26237063, 2013). "Moreover, CXCR4 activation in primary cultures of feline mammary carcinomas causes increase in the proliferative rate." (PMID 22417013, 2012). "They speculated that CXCR4-using variants might reduce breast cancer risk by binding to apoptosis receptors on hyperplastic and neoplastic breast duct cells." (PMID 22004990, 2011). "Furthermore, we evaluated the correlation between unmethylated CXCR4 and the hypermethylation of other genes strongly associated with breast cancer." (PMID 22220212, 2011). "Overexpression of CXCR4 is associated with metastasis and poor prognosis of breast cancer." (PMID 21915267, 2011). "Loss of DNA methylation in the CXCR4 promoter was detected in 67% of the breast cancer analyzed." (PMID 22220212, 2011). "Thus, we evaluated the expression pattern and methylation status of the CXCR4 gene, which encodes a well-known protein involved in breast cancer." (PMID 22220212, 2011). "Our results showed that the E2-dependent up-regulation of CXCL12 and CXCR4 that is associated with a down-regulation of CXCR7 could be pivotal for E2-induced growth of breast cancer cells." (PMID 21695171, 2011). "Our findings support the hypothesis that the low breast cancer incidence observed in women with HIV/AIDS is specifically linked to HIV variants that bind to CXCR4, a receptor that is commonly expressed on hyperplastic and neoplastic breast cells." (PMID 21179547, 2010). "Our data showing a reduced risk of breast cancer among women with CXCR4-tropic HIV may reflect an effect of CXCR4 at an intermediate stage of breast neoplasia." (PMID 21179547, 2010). "Additional studies are needed to confirm these observations and to understand how CXCR4 might reduce breast cancer risk." (PMID 21179547, 2010). "Based on these observations, we hypothesized that breast cancer risk would be lower among women with CXCR4-tropic HIV infection." (PMID 21179547, 2010). "To determine if the increased metastatic potential seen following hypoxia treatment was associated with the increased cell surface expression of CXCR4, we repeated the migration and invasion experiments in two human breast cancer cells lines, MDA-MB 231 and MCF7." (PMID 20492653, 2010). "Other interesting candidates include CXCR4, a receptor implicated in mediating metastasis of breast cancer cells through its ligand SDF-1, and CD14 and lipopolysaccharide-binding protein (LBP), which are implicated in Toll-like receptor signaling and LPS-mediated inhibition." (PMID 20346151, 2010). "Low breast cancer risk with HIV is specifically linked to CXCR4-using variants of HIV." (PMID 21179547, 2010).
breast carcinoma (continued). "In addition, organs commonly associated with being sites of breast cancer metastasis, such as lung, liver, lymph node, brain and bone, constitutively express the sole ligand for CXCR4, CXCL12." (PMID 17726466, 2007). "The CAF-driven CXCR4/CXCL12 axis may also stimulate the accumulation of protumorigenic lipid associated macrophages which supports an immunosuppressive microenvironment in breast cancer." (PMID 36588678, 2022). "Emerging evidence has revealed that C-X-C chemokine receptor 4 (CXCR4), a 352 amino acid rhodopsin-like G-protein-linked receptor, is overexpressed in many different types of human cancers, including osteosarcomas, glioma, prostate cancer, breast cancer and colorectal cancer." (PMID 35729596, 2022). "In addition to the well-known CXCL12/CXCR4 axis in directing the migration of breast cancer cells through the lymphatics, very few studies have been conducted to identify biomarkers associated with the lymph metastasis of breast cancer." (PMID 31443698, 2019). "In addition, CX3CR1 has been implicated in metastasis of prostate cancer cells and breast cancer cells to bone, and CXCR4 may have a particular role in bone metastasis." (PMID 29088715, 2017). "Hence, CXCR4 and CXCL12 form an important signaling axis between tumor cells and the tumor microenvironment, with the interaction influencing the adhesion, migration and invasion of tumor cells, reflecting the strong association of CXCR4 with breast cancer metastasis." (PMID 24475985, 2014). "Thus, clarifying the epidemiology of breast cancer in sub-Saharan Africa where CXCR4-using variants are prevalent may help evaluate the feasibility of testing and confirming or refuting this hypothesis." (PMID 22004990, 2011). "Blockade of CXCL12/CXCR4 signaling inhibits intrahepatic cholangiocarcinoma and breast cancer progression and metastasis via inactivation of canonical Wnt pathway." (PMID 40211853, 2026). "WWP1 promotes the ubiquitination and degradation of the oncogenic chemokine receptor CXCR4, thereby inhibiting breast cancer migration and metastasis." (PMID 40280416, 2025). "Bioinformatic analysis on RNA-seq data from MCF7 with MEG3 overexpression and MCF10A with MEG3 depletion led to the identification of CXCR4 as the major downstream mediator negatively regulated by MEG3 that facilitated breast cancer cell migration." (PMID 40548301, 2025). "CXCR4, a cell surface receptor with seven transmembrane-spanning domains that link to G protein, is significantly present in both initial and metastatic breast cancer cells and contributes to its metastasis." (PMID 40003882, 2025). "A significant positive correlation was found between mercury bioaccumulation and CXCR4 expression in breast cancer tissues." (PMID 40362664, 2025). "Whereas depletion of CXCR4 in breast cancer cells resulted in substantial suppression of cell migration." (PMID 40548301, 2025). "The model’s validity was further verified using breast cancer cells overexpressing metastasis-specific genes (CXCR4, claudin-2, Linc-ZNF469-3) and a patient-derived organoid (PDO) from a patient with advanced metastatic disease." (PMID 40510151, 2025). "CXCR4 in breast cancer plays a critical role in cancer progression by promoting growth as well as allowing for metastasis to distant tissues that express its ligand CXCL12 including lung and bone niches." (PMID 39982274, 2025). "Given the role of TGFβ-1 and CXCR4 in the breast cancer pathology especially their dysregulation in the said cancer, it is very important to develop better treatment interventions to address the same." (PMID 41348904, 2025). "Next, extensive bioinformatic analyses on RNA-seq data from MCF7 with MEG3 overexpression and MCF10A with MEG3 depletion suggested CXCR4 as the major target downstream MEG3 that mediated breast cancer cell migration." (PMID 40548301, 2025).